IL7 (interleukin 7)
Diseases named in the same sentence as IL7 in open-access papers (continued):
Sharing a sentence is not in itself a finding about the gene and the disease.
cancer (continued). "Previous clinical studies of rhIL-7 in HIV-infected or refractory cancer patients revealed that the relative frequency of regulatory T cells (Treg) expressing low-level CD127 was reduced due to IL-7-induced expansion of conventional T-cells." (PMID 40490502, 2025). "Recently, cytokines like IL2, IL‐7, IL‐10, and IL‐12 have been tested in clinical trials for the therapy of certain cancers (reviewed elsewhere)." (PMID 38813869, 2025). "Strategies targeting IL-7, such as designing IL-7 receptor antagonists or blockers of the IL-7 signalling pathway, are being investigated to mitigate cancer cachexia." (PMID 38675377, 2024). "The value of IL-7 has been studied thoroughly in cancer patients, radiation-induced lymphopenia patients, and HIV patients." (PMID 39684323, 2024). "Our study shows IL7 also increases central and effector memory T-cells in cancer immunity, with the T-cell response being compartment specific." (PMID 38554147, 2024). "Pathway analysis of splenic cells identified inhibition of T cell exhaustion signaling and activation of Th1, PD-1/PD-L1 cancer immunotherapy, NK cell, and IL-7 signaling pathways among the most significant effects predicted with BET-i." (PMID 38775157, 2024). "Initially, 1051 relevant studies were retrieved from the databases, excluding duplicated data and irrelevant articles and accepting articles that included biological properties of IL-7 and articles related to cancer." (PMID 38675377, 2024). "Many cytokines, including GM-CSF, IL-7, IL-12, IL-15, IL-18, and IL-21, have entered clinical trials for people with advanced cancer, while the FDA has approved interferon-alpha and IL-2." (PMID 38360737, 2024). "Due to its crucial role in the growth and development of various immune cells, IL-7 holds great promise for cancer therapy in a clinical setting." (PMID 38675377, 2024). "IL-7 plays a complex role in cancer pathology, and there has been increasing interest in its potential role in cancer cachexia." (PMID 38675377, 2024). "With these precautions, IL-7 therapy is expected to provide maximal therapeutic benefits while minimizing potential risks, making it a viable option for clinical use in cancer patients with TLP." (PMID 39763661, 2024). "Based on preclinical studies which corroborated that pharmacological administration of IL-7 induces T cell expansion with minimal toxicity, cancer has been investigated as potential therapeutic targets of IL-7 agonists." (PMID 38424167, 2024). "The supernatant from transfected cancer cells was found to enhance T-cell proliferation, with a volume of 10 μl corresponding to 1 ng of recombinant human IL7 protein." (PMID 38289597, 2024). "The L-R pair of IL7-(IL7R + IL2RG) was enriched between cancer cells and immune cells in EEC-II group, which plays a crucial role in the survival and differentiation of lymphocytes via IL7 receptor." (PMID 39112478, 2024). "Previous work has demonstrated that IL7 can induce naive T-cells to differentiate into a memory phenotype, and promote the proliferation and activity of effector T-cells against cancer." (PMID 38554147, 2024). "A notable clinical trial of IL-7 gene therapy in cancer treatment is the safety and feasibility in patients with relapsed or refractory haematological malignancies." (PMID 38675377, 2024). "The studies utilized MSCs as delivery systems for various therapeutic agents (interleukin 12, interleukin 7, doxorubicin, paclitaxel), reflecting the versatility of these cells in targeted cancer therapies." (PMID 39595821, 2024). "Many cytokines, including GM-CSF, IL-7, IL-12, IL-15, IL-18, and IL-21, have entered clinical studies for people with advanced cancer." (PMID 38360737, 2024). "The role of IL-7 in cancer cachexia continues to be a topic of great interest in the field of oncology." (PMID 38675377, 2024).
cancer (continued). "When comparing the normal, IBD, and cancer groups, we found that IL7 levels were higher in the cancer group compared to the control group but lower than in the IBD group." (PMID 38289597, 2024). "For example, one study found increased serum levels of IL-6 and IL-7 (cancer-suppressive) in CD, and increased TNF-α, eotaxin and growth-related oncogene (a chemokine) in UC patients." (PMID 37681925, 2023). "In this review, we show that phosphoflow cytometry has been applied to study a number of important cytokine signaling pathways in peripheral blood of cancer patients, including signaling induced by interferon, IL-6, and IL-7." (PMID 37741983, 2023). "IL‐7, which was first discovered in the 1980s, is a cytokine that elicits T‐cell response to target cancer cells." (PMID 36583472, 2023). "IL‐7 cytokine therapy has been tested in clinical studies of recurrent or refractory cancer, but showed unclear efficacy in terms of T‐cell regeneration and clinical benefit." (PMID 36583472, 2023). "PaTu8988T amoeboid cells were shown to secrete high levels of interleukins [such as interleukin-1α (IL-1α), IL-5, IL-6, IL-7, IL-8, and IL-9], as well as several chemokines involved in cancer progression." (PMID 37851808, 2023). "This promotes high levels of secretion of pro-inflammatory cytokines such as tumor necrosis factor-alpha (TNF-α), interleukin-7 (IL-7), and interleukin-12 (IL-12), strengthening the immune system’s surveillance and clearance of cancer cells." (PMID 37609372, 2023). "Overall, altered IFN, including both IFN-α and IFN-γ responses, IL-6, and IL-7 signaling pathways have been noted in cancer patients’ peripheral immune cells compared to those of healthy donors." (PMID 37741983, 2023). "Because of the immunomodulatory properties of IL-7, it has been tested in a clinical trial in patients with advanced cancers as monotherapy." (PMID 38019919, 2023). "The induction of a high level of IL-7 has been shown to indirectly contribute to cancer cell death in vivo by way of activation of natural killer (NK) cells in nude mice." (PMID 36869893, 2023). "In another clinical trial, recombinant human IL‐7 injection every other day for 2 weeks in refractory cancer patients increased CD3+, CD4+, and CD8+ lymphocytes in a dose‐dependent manner." (PMID 36583472, 2023). "The action of interleukin-7 (IL-7) as a cytokine has been observed in many cellular processes, both in normal cells of the immune system and in some cancer cells." (PMID 35794603, 2022). "Recently, clinical trials have been undertaken to improve treatment outcomes using IL-7 or IL-15 and ICIs in combination in various cancers (NCT03901573, NCT04594811, NCT04332653, NCT04984811)." (PMID 36291893, 2022). "Although the antitumor role of IL-7 in combination with cancer vaccine has been revealed, there is still a “dark side” that needs to be emphasized." (PMID 36389666, 2022). "Second, in the context of the high interest in the clinical study results of the combined treatment with IL-7 or IL-15 and ICIs in advanced cancers, α can directly suggest a subgroup that can expect a good treatment response to immunotherapy." (PMID 36291893, 2022). "We then summarize the recent progress in the use of IL-7 and IL-7Rα in cancer immunotherapy and discuss their potential for therapeutic applications." (PMID 36142322, 2022). "Numerous preclinical trials have evaluated the potential role of IL-7 as an adjuvant to strengthen the effectiveness and long-term responsiveness of cancer vaccines." (PMID 36389666, 2022). "In this review, we first summarize the roles of IL-7 and IL-7Rα and their downstream signaling pathways in immunity and cancer." (PMID 36142322, 2022). "In this review, we summarize the roles of IL-7, IL-7Rα, and their downstream signaling pathways in immunity and cancer development." (PMID 36142322, 2022).
cancer (continued). "The N1 phenotype with high levels of TNF-α, IL-2, IL-4, IL-7, and IL-10 expression induces a cytotoxic effect to cancer cells and hampers cancer cell progression." (PMID 35267547, 2022). "Clinical trials of cancer vaccines combined with IL-7 as an adjuvant for the treatment of malignancy." (PMID 36389666, 2022). "Although boosted T cell expansion and enhanced T cell memory were evidenced in clinical trials when administrating IL-7 as an adjuvant combined with cancer vaccines, the clinical outcomes of cancer patients are still far from satisfactory." (PMID 36389666, 2022). "Previous studies have shown that IL‐7 can act on cancer cells in an autocrine manner to increase cell proliferation." (PMID 36054746, 2022). "Based on its promising therapeutic effects, IL-7 expressing CAR-T cells are being used in various clinical trials for cancer immunotherapy." (PMID 36142322, 2022). "This review will help in the development of cancer immunotherapy regimens based on IL-7 and IL-7Rα, and will also advance their exploitation as more effective and safe immunotherapy tools." (PMID 36142322, 2022). "These facts highlighted the feasibility to apply IL-7 as an adjuvant in combination with cancer vaccines." (PMID 36389666, 2022). "IL-7 and IL-7R are thought to be critical for regulating the impaired immune system of cancer patients." (PMID 36142322, 2022). "Extensive experiments are needed to verify the feasibility of IL-7 in cancer immunotherapy, as well as its side effects or other adverse effects." (PMID 36142322, 2022). "Increased administration of IL-7 can boost the specific memory immune responses against cancer and viral infection." (PMID 36389666, 2022). "Here we selectively summarized the performance of IL-7 as an adjuvant in combination with cancer vaccines in preclinical settings." (PMID 36389666, 2022). "More preclinical and clinical studies are encouraged to explore the potential role of IL-7 as an adjuvant for the development of cancer vaccines." (PMID 36389666, 2022). "Recently, some clinical studies attempt to administer recombinant human IL-7 in cancer patients subcutaneously as an adjuvant for cancer vaccines." (PMID 36389666, 2022). "Cancer cell vaccines transfected with the IL-7 gene to combat malignant diseases have been extensively explored." (PMID 36389666, 2022). "IL-2 and IL-7 have been well demonstrated to enhance the T cell responses, indicating the potential role of IL-2 in combination with IL-7 as adjuvants for cancer vaccines." (PMID 36389666, 2022). "This identified 3 matrisome genes, CTHRC1, PDGFA and IL7 to be prominent candidates of which only CTHRC1 was upregulated in pan-cancer and 3 individual cancers making it the matrisome gene of interest." (PMID 36190948, 2022). "Preclinical researches bring inspiring results for the rationale to apply IL-7 as an adjuvant for cancer vaccines while further clinical trials enhance this notion." (PMID 36389666, 2022). "This research highlighted the possibility to apply Fc-fused IL-7 as an adjuvant to strengthen the cellular immunity induced by vaccines in the genital mucosa to struggle against cancers." (PMID 36389666, 2022). "Of these genes, CTHRC1, PDGFA, and IL7 were also shortlisted as matrisome genes of interest in the pan-cancer analysis." (PMID 36190948, 2022). "It is now known that IL-7 induces the proliferation of a variety of cancers, such as leukemia and lymphomas." (PMID 35794603, 2022). "The dose of IL-7 injection varies from 10 μg/kg to 20 μg/kg in cancer patients while at least four doses were administered." (PMID 36389666, 2022). "The IL‐7 signaling pathway is also involved in many types of cancers, including hematologic malignancies as well as solid tumors." (PMID 36054746, 2022).
cancer (continued). "explored Mycobacterium smegmatis delivering a fusion protein comprising human macrophage migration inhibitory factor (MIF) and IL-7 as cancer vaccines to struggle against tumors." (PMID 36389666, 2022). "Our data suggest that IL7-Fc would be clinically beneficial in cancer patients receiving adoptively transferred T cells under lymphopenic conditions." (PMID 34440787, 2021). "More recently, scientists tried to apply IL-7 to CAR-T cells given the great success chimeric antigen receptor (CAR)-engineered T cells showed in cancer treatment." (PMID 34925323, 2021). "IL-7 regulates T cell proliferation and survival and has been used in immunotherapeutic approaches for cancer therapies due to its immune reconstructive and activating properties." (PMID 34654395, 2021). "While IL7 is an important candidate immunomodulator for cancer therapy, its use in the clinic is limited by its short half-life in the serum." (PMID 33574842, 2021). "Regarding myokines, we assessed irisin, OSM, osteonectin, IL-6, IL-15, and IL-7 on account of evidence supporting the utility of these myokines in the context of cancer prevention and control." (PMID 33555464, 2021). "Increased IL-7 usage can also enhance pathogen-specific memory T cell responses against cancer and chronic viral infections." (PMID 34956167, 2021). "T cells were co-cultured with cancer spheroids for 48 h in OP9 medium supplemented with 5 ng/ml IL-7 and 5 ng/ml IL-15." (PMID 34099861, 2021). "Interleukin-7 is a critical regulatory T cell growth and survival factor in autoimmunity and cancer." (PMID 34276694, 2021). "IL‐7 has potential clinical applications including enhancing immune reconstitution during lymphopenic conditions, for example, cancer patients receiving chemo‐ or radiation therapy." (PMID 34525268, 2021). "IL-7 has been used as an activator to augment mature T cell immune responses against chronic viruses and cancers." (PMID 34956167, 2021). "On the other hand, IL-7 operates at the foundations of T-cell and innate lymphoid cell (ILC) development and homeostasis and has been associated with cancer." (PMID 32849527, 2020). "Due to the deleterious role of Tregs in cancer immunotherapy, many investigators are now exploring the role of IL-7 in potentiating checkpoint modulators or T cell therapies, as discussed in greater detail later in this review." (PMID 30842774, 2019). "IL-7 plays a pivotal role in immunity, and potentially confers protection against cancer via its effect on T lymphocytes." (PMID 31185636, 2019). "Here, we developed and characterized a fully human monoclonal antibody against IL-7Rα, providing clear proof-of-concept for the development of antibody-based treatments for T-ALL and other cancers relying on IL-7/IL-7R-mediated signals." (PMID 30850736, 2019). "Fold change in IL-7 concentration in M1 cancers was 3.1 (0.9–11.1) against 2.3 (1.8–3.1) in M0 cancers; p = 0.556." (PMID 31185636, 2019). "Still, it is surprising as, even with the assumed beneficial role of IL-7, extensive knowledge on cytokine status in cancers to be treated with it ought to be a prerequisite." (PMID 31185636, 2019). "With the help of this new model, we show the importance of the heterogeneity in the immune response (which impacts the secretion level of IL-7) on the cancer detection times." (PMID 29554938, 2018). "Using IL-7 to boost immunity with IL-7 has been shown to be beneficial in patients with incurable malignancy by preventing disease recurrence and facilitating restoration of immune function." (PMID 29904108, 2018). "Recently, IL-7 was proposed to play a role in the pathogenesis of mammary gland carcinogenesis, promoting the survival and development of cancer cells in culture, with its expression being connected to poor prognosis in human samples." (PMID 30648081, 2018).
cancer (continued). "Owing to its central role in innate and adaptive immunity, IL-7 has been listed as one of the “Top Agents with High Potential for Use in Treating Cancer” by the panel of experts at the National Cancer Institute Immunotherapy Agent Workshop in 2007." (PMID 27866242, 2017). "Interleukin (IL)-7 is a cytokine essential for protective immunity, and it is considered as a promising agent for cancer immunotherapy." (PMID 27866242, 2017). "Clinical trials conducted in bone-marrow transplant and cancer patients, indicated that IL-7 therapy increased T-cell expansion, survival, thymic output, and T-cell receptor repertoire diversity." (PMID 29261677, 2017). "In the context of cancer disease, interleukin (IL)-7 is viewed as a key therapeutic factor, while substantially less attention has been devoted to its possible association with the disease development." (PMID 27866242, 2017). "Therapeutic administration of IL-7 has been evaluated for the treatment of cancer, chronic HIV infection and transplantation in which T-cell reconstitution is required." (PMID 29261677, 2017). "In our previous studies, we demonstrated that licorice polysaccharides not only upregulate IL-7 expression but also inhibit proliferation of cancer cells in vitro." (PMID 29246138, 2017). "It has been shown that adjuvant IL-7 can enhance the efficacy of cancer vaccine-induced T cell responses by antagonizing multiple immunoinhibitory mechanisms." (PMID 28939858, 2017). "For instance, IL-7 is significant in cancer immunotherapy, by promoting stimulation, activation, survival and homeostasis of immune effector cells." (PMID 29246138, 2017). "Since the adjuvant effects of IL-7 in enhancing cancer vaccine-induced T-cell responses have recently been demonstrated, we posit that the IL-7Rα+ polyfunctional CD4+ effector cells arising after ACT would be amenable to adjuvant IL-7." (PMID 28939858, 2017). "Here we show that co-expression of two cytokine members of the common cytokine receptor γ-chain family, IL-21 and IL-7, in whole-cell cancer vaccines boosts antitumor immunity in a CD4+ and CD8+ T cell-dependent fashion." (PMID 27571893, 2016). "These facts warrant future development of IL-21 and IL-7 co-expressing whole-cell cancer vaccines and their relevant combinatorial regimens." (PMID 27571893, 2016). "The aim is to determine the effect of the polysaccharides on IL-7 gene expression, effect of IL-7 on proliferation of T lymphocytes and inhibitory potential of the polysaccharides on cancer cells." (PMID 27401917, 2016). "Clinical evaluation of IL-7 in human cancer is based on enhancement of adaptive immunity for improving T-cell survival and numbers, as well as T-cell repertoire diversity." (PMID 28036019, 2016). "Among other cytokines, IL-7 has entered clinical trials for having a potential for adoptive immunotherapy in cancer therapy." (PMID 27401917, 2016). "IL-7 is an important cytokine in cancer immunotherapy and it has potential for adoptive immunotherapy." (PMID 27401917, 2016). "It is therefore paramount that the upregulation of IL-7 leads to augmentation of T lymphocytes which are important in cancer immunotherapy." (PMID 27401917, 2016). "The sustenance of adaptive memory against cancer is also a feature worth noting for IL-21 and IL-7 co-expressing cancer vaccines, since immune memory is responsible for long-lasting protection from cancer recurrences." (PMID 27571893, 2016). "In the clinical trials reported in 2006, 2008 and 2010, patients with different kinds of cancers such as metastatic melanoma or sarcoma were injected subcutaneously with different doses of IL-7." (PMID 25955647, 2015). "In this review, we will focus on the mechanism of action and applications of IL-7 in cancer immunotherapy and the potential restrictions for its usage." (PMID 25955647, 2015). "Modulation of the IL-7 axis is an ideal tool for repairing damaged immune systems in cancer patients, particularly those who received chemotherapy." (PMID 25955647, 2015).